ASL (argininosuccinate lyase)
Diseases named in the same sentence as ASL in open-access papers (continued):
Sharing a sentence is not in itself a finding about the gene and the disease.
cancer (16 papers, 2013 to 2026). A tumor composed of atypical neoplastic, often pleomorphic cells that invade other tissues. "In the urea cycle, whose rewiring has been described in cancer to support anabolism, argininosuccinate and aspartate are converted into arginine and fumarate by the enzyme argininosuccinate lyase (ASL)." (PMID 37689804, 2023). "The intracellular increase of this oncometabolite pressures cancer cells to metabolize arginine to form argininosuccinate by the enzyme argininosuccinate lyase (ASL)." (PMID 35745875, 2022). "Although the loss of ASS1 expression is reported in a variety of cancers, we show reduced expression of both ASS1 and ASL in ccRCC tumors." (PMID 34861885, 2021). "With the expressions of ASS and ASL genes conferring resistance to L-arginine deiminase (ADI) which is undergoing Phase III clinical trial, BCA-M offers the advantage of a broader spectrum of susceptible cancer cells." (PMID 33050217, 2020). "The most marked cancer-related difference seems to be associated with ODC and ARG2 expression patterns, mostly changed from very strong to strong (with DDAHs) or moderate (with PRMTs), and with loosening of ASS1 and ASL association with each other as well as other pathway enzymes." (PMID 34439753, 2021). "In cancer cells, the UC is reconfigured/reorchestrated to support high anabolic demand, often involving the dysregulation of key enzymes such as ASS1, ASL, OTC and CPS1." (PMID 42074106, 2026). "The de novo biosynthesis of arginine, catalyzed by the enzymes argininosuccinate synthetase 1 (ASS1) and argininosuccinate lyase (ASL), is frequently dysregulated in cancer." (PMID 40535116, 2025). "Cancer cells are dependent on extracellular arginine because of the decreased expression of arginine-synthesizing enzymes, argininosuccinate synthase (ASS1) and argininosuccinate lyase (ASL)." (PMID 35898872, 2022). "Cancer cells are addicted to external arginine, as they are unable to synthesize it because they do not express arginine synthase 1 (ASS1), which, in combination with argininosuccinate lyase (ASL), synthesizes arginine in normal cells from citrulline and aspartate." (PMID 37568713, 2023). "Indeed, the activity of the key enzymes involved in NO production, namely ASS1, ASL, arginase and NOS, are frequently altered in various types of cancers, enabling us to identify vulnerabilities in NO-related pathways and to design novel anti-cancer drugs that target these enzymes." (PMID 30082427, 2018). "As a result, arginine deprivation has emerged as an attractive therapy in cancers lacking ASS1 (and ASL)." (PMID 34861885, 2021).
tumor (14 papers, 2020 to 2026). "Similar result was obtained in pLGG with 96%, 93%, and 91% of tumours being deficient in ASL, ASS1, and OTC, respectively." (PMID 35782058, 2022). "We found that Arg2 is the main metaboliser in 88% of MB tumours and that these were deficient in recycling enzymes ASL, ASS1, and OTC in 79%, 88%, and 85% of cases." (PMID 35782058, 2022). "The presence of enzymes involved in arginine biosynthesis, like argininosuccinate synthase (ASS1) and argininosuccinate lyase (ASL), plays a crucial role in determining a tumor’s arginine auxotrophy." (PMID 39590860, 2024). "Interestingly, we also observed a heterogeneous distribution of argininosuccinate even if ASS1 and ASL were overall suppressed in these tumours." (PMID 41213938, 2025). "Levels of argininosuccinate synthetase 1 (ASS1) and argininosuccinate lyase (ASL), key enzymes in arginine metabolism, were increased in primary ESCC tumors but decreased in lymph-metastatic tumor tissues." (PMID 39090094, 2024). "In vivo, Arginine is synthesized from aspartate or citrulline through argininosuccinate synthetase (ASS1) and argininosuccinate lyase (ASL), which act as key regulators in determining the arginine-dependency of tumor cells." (PMID 35178349, 2022). "Our study here uncovers two potential metabolic tumor suppressors in ccRCC—the urea cycle enzymes ASS1 and ASL." (PMID 34861885, 2021). "We employed a combination of computational, genetic, and metabolomic tools along with in vivo animal models to establish a tumor-suppressive role for ASS1 and ASL in ccRCC." (PMID 34861885, 2021). "Immunohistochemistry (IHC) staining showed that while the UCEs CPS1, ASS1, ASL, and ARG1 were highly expressed in the periportal (zone 1) and midzonal areas (zone 2) in healthy control mice, they were expressed at various levels in the end-stage tumor tissues." (PMID 41512056, 2026). "As the importance of repressing mitochondrial ARG2 as a metabolic tumor suppressor in ccRCC has been established, we now focused on the cytosolic urea cycle enzymes ASS1 and ASL that convert citrulline and aspartate to arginine and fumarate via argininosuccinate." (PMID 34861885, 2021). "Moreover, several pivotal enzymes involved in amino acid metabolism process and urea cycle were identified with decreased lysine acetylation levels in HCC tumor tissues, such as GLUD1, ASL, GOT2 and so on." (PMID 33093847, 2020). "Besides, overexpression of ASL or ASS1 promotes cell proliferation, indicating that TET2-urea cycle-mTORC1 axis may play an important role in tumor growth." (PMID 37550284, 2023).
inherited metabolic disorder (1 paper, 2024). "Moreover, functional enrichment analysis by STRING showed that BTD, ASL, GBE1 and AGL are among 726 genes co-expressed during inherited metabolic disorder." (PMID 38592052, 2024).
ASL also shares sentences with these, for which no sentence is quoted: genetic disorder (3 papers); Hyperornithinemia (3); Metabolic Disorders (2); acute liver failure (1); Angelman syndrome (1); Cirrhosis (1); clear cell renal cell carcinoma (1); dimethylglycine dehydrogenase deficiency (1); Escobar syndrome (1); GAMT deficiency (1); Glycogen storage disease Ia (1); holocarboxylase synthetase deficiency (1); liver disease (1); MELAS (1); myocardial infarction (1); non-small cell lung carcinoma (1); Pyruvate carboxylase deficiency (1); Spastic paraplegia 15 (1); spondylometaphyseal dysplasia (1); X-linked adrenoleukodystrophy (1).